TLR4 (toll like receptor 4)
Diseases named in the same sentence as TLR4 in open-access papers (continued):
Sharing a sentence is not in itself a finding about the gene and the disease.
influenza (continued). "Thus, the increased resistance of TLR4-/- and C3H/HeJ mice, coupled with the ability of many distinct TLR4 antagonists to block influenza-mediated cytokine production, ALI, and lethality, strongly support a critical role for TLR4 signaling in influenza-induced disease." (PMID 34282358, 2021). "However, the role of TLR4 in influenza-induced lethality has been challenged by other study." (PMID 32326516, 2020). "A liposomal formulation containing TLR4 and TLR7 agonists was also shown to be an effective mucosal adjuvant for an influenza vaccine in mice." (PMID 37179389, 2023). "In mice, TLR4 and TLR7 worked additively to induce antigen-specific IgG and provided protection against influenza challenges when this combination was used as an adjuvant." (PMID 35746503, 2022). "In contrast to this, the combination of TLR4 and TLR7 agonists reduced mortality and morbidity in mice against virulent challenges of influenza when it was used as an adjuvant with influenza antigens." (PMID 35746503, 2022). "Third, through network pharmacology and molecular docking analysis, the TLR4/NF-κB p65 signaling pathway and HIF-1α/IL17 signaling pathway were found to be highly related to the anti-inflammatory action of HSSD in treating influenza." (PMID 36386710, 2022). "Next, eight key targets were identified, including TLR4, CD14, MyD88, NF-κB p65, HIF1 α, VEGF, IL17A, and IL6, which were verified to be key targets for HSSD in the treatment of influenza." (PMID 36386710, 2022). "A549 cells infected with influenza and treated with curcumin showed inhibition of influenza-induced expression of TLR2, TLR4, and TLR7, as well as inhibition of activation of MyD88- and TRIF-dependent signaling pathways." (PMID 34282358, 2021). "Recent publications have further demonstrated that the combinations of synthesized TLR4, TLR7, and TLR7/8 ligands were potent adjuvants for recombinant influenza HA vaccines in different animal models." (PMID 33430259, 2021). "When challenged with influenza PR8 (LD90), wildtype mice succumbed to infection, while TLR4-/- mice were refractory (p<0.0001), as previously reported." (PMID 34282358, 2021). "This review will examine how antagonizing TLR4 signaling has been effective experimentally in ameliorating ALI and lethal infection in challenge models triggered not only by influenza, but also by other ALI-inducing viruses." (PMID 34282358, 2021). "In murine models of fatal coronavirus (MERS and SARS) and influenza pneumonias, TLR3–TLR4 synergism is universal, such that antagonizing or deleting TLR4, which is specifically activated by bacterial lipopolysaccharides, prevents death." (PMID 33672738, 2021). "This aggravates viral replication and transmission in influenza, HBV and HIV via TLR4 activation, which is a pattern-recognizing receptors (PRR) for LPS." (PMID 33243230, 2020). "We previously reported that the Toll-like receptor 4 (TLR4) antagonist Eritoran blocks acute lung injury (ALI) therapeutically in mouse and cotton rat models of influenza." (PMID 31064834, 2019). "Used as an adjuvant with either influenza or TB antigens triggers robust TH1 and IgG2a responses that are superior to alhydrogel even when the latter includes a Toll-like receptor 4 (TLR4) agonist." (PMID 30622742, 2019). "Changes in expression of different toll-like receptors (TLRs) (TLR2, TLR3, TLR4, TLR7, TLR8, and TLR9) have been reported before in human monocytes and dendritic cells from seasonal influenza infected patients." (PMID 30682165, 2019). "Adjuvants based on toll-like receptor agonists including TLR4 and TLR9 agonists used in pandemic and “universal” influenza vaccines, respectively, have shown excellent results in phase I trials." (PMID 29326687, 2017). "Recent studies suggest that influenza-induced lethality and ALI are due to the TLR4-stimulating effects of DAMPs such as OxPAPC and HMGB1, which are both TLR4 agonists." (PMID 28106157, 2017).
influenza (continued). "In this study, we investigated the adjuvant activity of CIA06, an adjuvant system that is composed of a toll-like receptor 4 agonist de-O-acylated lipooligosaccharide (dLOS) and aluminum hydroxide, on the H1N1 pandemic influenza vaccine Greenflu-S® in mice." (PMID 27891512, 2016). "As expected, all TLR ligands protected against lethal influenza pneumonia, but pre-stimulation with FSL-1 (TLR2 ligand) or msbB LPS (weak TLR4 agonist) provided the best protection, both producing a 10-fold increase in MLD50." (PMID 21375734, 2011). "Similarly, SERPINE2 correlated positively with TLR4 and RIG-I in COVID19 but negatively in influenza." (PMID 40825056, 2025). "TLR4 contribution was not demonstrated in TLR4 KO mice with influenza infection, thereby affirming the predominant involvement of TLR3 and TLR7 activation in response to influenza virus." (PMID 38835761, 2024). "Our previous studies suggest that the addition of a toll-like receptor (TLR4) agonist to SVV can overcome the suppressive effects of IL-10 and improve the IFNγ response and markedly improve the IFNγ:IL-10 ratio and GrB response to influenza challenge." (PMID 35128529, 2021). "The work shown here extends these previous studies by demonstrating that lipidated imidazoquinolines in an aqueous formulation, with or without the addition of a TLR4 agonist, also serve as potent influenza adjuvants." (PMID 32210973, 2020). "As a follow-up of these studies, an influenza vaccine formulated with both 1Z105 and 1V270 was shown to function in vivo through TLR4 and TLR7 activation without any significant off-target effect, and it succeed in inducing protective immunity." (PMID 32765484, 2020). "GLA-AF, an emulsion-free aqueous formulation with glucopyranosyl lipid adjuvant, a TLR-4 agonist, has been evaluated for ID immunization with an H5-VLP influenza vaccine and showed low skin reactogenicity in guinea pigs and stimulated strong anti-H5 responses in C57BL/6 mice." (PMID 31682624, 2019). "In the case of influenza and other microbial infections, therapeutic approaches that interfere with either virus- or DAMP-induced TLR4 signaling may open up new possibilities for treatment against pathogenesis (11, –, 14, 21)." (PMID 29535197, 2018). "Toll-like receptor 4 (TLR4) agonists, such as monophosphoryl lipid A (MPL) or glucopyranosyl lipid adjuvant (GLA), when combined with alum or in oil-in-water formulation, also exhibited potential for use as adjuvant for influenza vaccines." (PMID 27891512, 2016). "Overall, TLR4 agonist-based adjuvants (MPL and GLA formulations) robustly enhance vaccine efficacy by promoting broad, durable, and cross-protective immune responses, making them powerful tools for the development of the next generation of universal influenza vaccine." (PMID 41012165, 2025). "GLA, a Th1-inducing synthetic TLR4-agonist adjuvant that is a non-toxic derivative of lipopolysaccharide, has led to improved immunogenicity of investigational vaccines for tuberculosis and influenza." (PMID 39775205, 2024). "Interestingly, the studies of SP-A and SP-D interactions with TLRs were carried out in vitro only, thus their role in influenza infection in vivo or its interplay with TLR4 has not yet been elucidated." (PMID 34282358, 2021). "Also in influenza infection, HMGB1 may induce IL-6 and IL-8 production, activating DCs via the TLR-4 pathway." (PMID 32724296, 2020). "Indeed, complete TLR-deficient mice (due to a lack of TLR2, TLR4 and Unc93) showed significant deficits in CD5+ B-1 cell responses following influenza infection." (PMID 31433296, 2019). "In conclusion, our study suggested that TLR4, CD14, MyD88, NF-κB p65, HIF1 α, VEGF, IL17A, and IL6 in the TLR4/NF-κB p65 signaling pathway and HIF-1α/IL17 signaling pathway may be the key targets for the identified active compounds of HSSD to treat influenza by inhibiting inflammatory responses." (PMID 36386710, 2022).
influenza (continued). "Thus, the TLR4, CD14, MyD88, and NF-κB p65 in TLR4/NF-κB p65 signaling pathway, HIF1 α, VEGF, IL17A, and IL6 in HIF-1α/IL17 signaling pathway may be the targets responsible for the anti-inflammatory function of HSSD in treating influenza." (PMID 36386710, 2022). "Since both B cell-intrinsic and -extrinsic TLR signals influenced EFR magnitude and kinetics, we tested whether LPS, a TLR4 agonist that initiates both MyD88 and TRIF signaling, could overcome the lack of EFRs induction after s.c. immunization with influenza virions in alum." (PMID 37407556, 2023).
mastitis (94 papers, 2009 to 2025). Inflammation of breast tissue during lactation or postpartum due to an obstructed duct or infection. "Low degree endotoxemia causes persistent damage and mastitis by activating the TLR4-cGAS-STING-NF-κB/NLRP3 signaling pathway." (PMID 40303309, 2025). "TLR4 polymorphisms have been associated with resistance to mastitis and improve the milk yield and quality, likely due to a reduced interaction between TLR4 and its adaptor proteins." (PMID 39609525, 2024). "TLR4 gene polymorphisms and mastitis susceptibility were found to significantly correlate in sheep and cattle." (PMID 37756095, 2023). "The epithelial cells of the inner surface of the mammary gland play a key role in recognizing mastitis-causing pathogens by synthesizing toll-like receptors (TLR2 & TLR4)." (PMID 36911690, 2023). "For instance, sequence analysis variations of the TLR2 and TLR4 genes were linked to endometritis and mastitis in river buffalo." (PMID 37756095, 2023). "Low-grade endotoxemia impaired host ALP by activating Neu, causing persistent injury and mastitis by activating the TLR4-cGAS-STING-NF-κB/NLRP3 signatures." (PMID 36451232, 2022). "This gene has been described as highly variable in cattle, and many TLR4 polymorphisms and haplotypes have been associated with milk somatic cell count and susceptibility to mastitis." (PMID 35264251, 2022). "Overall, the results of this study showed that the C4BPA gene through TLR4/NF-κB played a significant role in regulating the expression of all the major genes of immunity and inflammation factors associated with mastitis in dairy cattle." (PMID 35173767, 2021). "In this regard, activation of TLR4 is linked to the expression of pro-inflammatory cytokines and the activation of NF-kappaB signaling pathway in mastitis." (PMID 32754201, 2020). "Alleles of Tlr4, a bacterial associated molecular pattern receptor, are linked with the occurrence of mastitis in cattle." (PMID 29117179, 2017). "Toll-like receptor 4 (TLR4) mediated activation of the nuclear transcription factor κB (NF-κB) signaling pathway by mastitis initiates expression of genes associated with inflammation and the innate immune response." (PMID 25706977, 2015). "Similarly, SNP analysis of the TLR4 promoter has identified associations between specific polymorphisms and susceptibility to bovine subclinical mastitis, highlighting the potential of genetic selection in improving disease resistance." (PMID 40141146, 2025). "The studies demonstrated that the occurrence, development, susceptibility and resistance to mastitis are regulated by a gene network composed of several genes, among which the Toll-like receptor 4/nuclear factor-κB (TLR4/NF-κB) signaling pathway is an important regulatory pathway." (PMID 36231106, 2022). "Furthermore, methionine and arginine down-regulated the levels of TLR4 and IL1β in LPS-induced mastitis, which caused the excessive regulation of inflammatory changes, and thus damaged the cells." (PMID 32927884, 2020). "On the other hand, we selected LPS as the inflammatory challenge, taking into consideration that E. coli is one of the major mastitis-causing pathogens that induces acute inflammation of the mammary gland through the activation of the LPS/TLR4-mediated signaling pathway." (PMID 32466097, 2020). "Therefore, it is suggested that the markers of the TLR4 gene can be used as molecular markers for mastitis resistance in buffaloes, due to their association with somatic cell counts." (PMID 33251259, 2020). "Additionally, single gene polymorphisms (CXCR1, MAP4K4) and their signaling pathways (TLR4/NF-κB) served as genetic markers for mastitis in different cow populations." (PMID 31447828, 2019). "Tlr4 has also been linked to a number of the systemic symptoms of mastitis." (PMID 29117179, 2017). "The TLR4 gene on BTA8 was found in mastitis association and expression studies." (PMID 19508288, 2009).
mastitis (continued). "The mRNA levels of TLR4, MyD88, IKKβ, and NF-κB p65 were significantly different between the model group and the non-mastitis group (p < 0.01)." (PMID 40266913, 2025). "Another study reported that TLR4/NF-κB is involved in the inflammatory response related to bovine mastitis." (PMID 39852532, 2025). "It is then transported to the TLR4-MD2 protein complex, activating TLR4 and triggering an inflammatory response, such as rumenitis, mastitis, endometritis, laminitis, and hepatitis 17-20." (PMID 40303309, 2025). "Nanocurcumin alleviates inflammation and oxidative stress in LPS-induced mastitis by activating Nrf2 and inhibiting TLR4-mediated NF-κB and HMGB1 signaling pathways." (PMID 41012726, 2025). "In the mammary gland, repeated LPS exposure also impairs ALP activity, thereby contributing to mastitis through activation of the TLR4-cGAS-STING-NF-κB/NLRP3 pathway." (PMID 41139776, 2025). "TLR4 is the most up-regulated gene (2.5040 ± 0.21) in mastitis Barki ewes, whereas GST is the most down-regulated gene (0.4490 ± 0.05)." (PMID 40542007, 2025). "Recently, the mechanism of natural product for treating mastitis has focused on the TLR4/NF-κB signaling pathway." (PMID 39852532, 2025). "Bioactive compounds and probiotics have been recognized as promising therapeutic agents for the prevention and treatment of mastitis by modulating the TLR2/TLR4/NF-κB signaling pathway." (PMID 40871398, 2025). "It has been demonstrated that probiotics and bioactive compounds have the ability to modulate the TLR2/TLR4/NF-κB pathway, potentially reducing the inflammatory response and aiding in the prevention of mastitis." (PMID 39199398, 2024). "This review summarizes recent research on the role of the TLR2/TLR4/NF-κB signaling pathway in mastitis." (PMID 39199398, 2024). "This is followed by the downregulation of NF-κB-p38 and TLR4/NF-κB/MAPK signaling to mitigate mastitis in MMECs." (PMID 39199398, 2024). "By targeting the TLR2/TLR4/NF-κB signaling pathway, we can potentially find a promising therapeutic approach to reduce mastitis." (PMID 39199398, 2024). "The in vitro investigations discussed in this review strongly support the idea that the TLR2/TLR4/NF-κB signaling pathway plays a crucial role in the development of mastitis in dairy cows." (PMID 39199398, 2024). "Based on the existing findings, it has been concluded that bioactive compounds targeting the TLR2/TLR4/NF-κB signaling pathways show promise in mitigating mastitis." (PMID 39199398, 2024). "Based on available data, this review aims to summarize the research progress on the critical role of TLR2/TLR4/NF-κB signaling pathway activation in the prevention and treatment of mastitis." (PMID 39199398, 2024). "Overall, this review highlights the significance of targeting the TLR2/TLR4/NF-κB signaling pathway to develop effective therapeutic strategies against mastitis, which can enhance dairy cow health and reduce economic losses in the dairy industry." (PMID 39199398, 2024). "The pathogenic mechanisms of mastitis involve the activation of Toll-like receptors (TLRs), specifically TLR2 and TLR4." (PMID 39199398, 2024). "A strong association between TLR4 gene SNPs and somatic cell counts has been identified in Murrah buffaloes, suggesting that the TLR4 gene can be used as a molecular marker for mastitis resistance in buffaloes." (PMID 38520296, 2024). "Curcumin reduced inflammation, MPO, cytokines, TLR4 expression and NF-κB activation in LPS-induced mastitis model." (PMID 38377032, 2024). "Recently a study reported the polymorphisms in TLR4 gene on promoter and 5′ untranslated region (5′UTR) were significantly associated with mastitis in cattle mammary gland tissue." (PMID 39199398, 2024). "Recent in vitro studies have emphasized the importance of the TLR2/TLR4/NF-κB signaling pathway in the development of mastitis, suggesting its potential as a therapeutic target." (PMID 39199398, 2024).